PSMA5 (proteasome 20S subunit alpha 5)
Diseases named in the same sentence as PSMA5 in open-access papers:
PSMA5 is named in the same sentence as 48 diseases in open-access papers, as found by Europe PMC text mining. Sharing a sentence is not in itself a finding about the gene and the disease. The quoted sentences say what the papers report.
prostate carcinoma (7 papers, 2022 to 2025). A carcinoma that arises from epithelial cells of the prostate gland. "According to some studies, PSMA5 was considered to promote the tumour progression of prostate cancer and lung adenocarcinoma while its expression was associated with good prognoses in breast cancer." (PMID 38238671, 2024). "Studies have shown that PSMA5 is related to the pathogenic process of prostate cancer and colon cancer and upregulated in lung adenocarcinoma." (PMID 36424389, 2022). "High PSMA5 expression is linked to the poor prognosis of patients with prostate cancer." (PMID 38415977, 2024). "In June 2024, a clinical trial of the prostate-specific membrane antigen (PSMA)-targeted radiotherapeutic agent [211At] PSMA-5 was initiated in patients with castration-resistant prostate cancer." (PMID 40943522, 2025). "[211At]PSMA5 exhibited excellent tumor growth suppression in xenograft models of prostate cancer, with minimal side effects." (PMID 36344651, 2023). "Apigenin induced apoptosis in prostate cancer cells, which was accompanied by the downregulated expression of PSMA5." (PMID 35421138, 2022). "[211At]PSMA5 could be a new possible targeted α-therapy for prostate cancer, specifically metastatic CRPC, and future translational prospective trials are warranted." (PMID 36344651, 2023). "In this study, we evaluated the characteristics of a novel 211At-labeled PSMA compound ([211At]PSMA5) and its therapeutic effect in a mouse xenograft model of prostate cancer and compared it with two closely related new derivatives, namely [211At]PSMA1 and [211At]PSMA6." (PMID 36344651, 2023). "Although PSMA5 has been found to be lowly expressed in gliomas, in many other tumors such as LUAD and prostate cancer, it shows an upregulated expression level." (PMID 38415977, 2024). "In addition to this, consistent with the findings that PSMA5 plays an oncogenic role in LUAD and prostate cancer, our data showed that knockdown of PSMA5 resulted in inhibited HCC cell migration and invasion." (PMID 38415977, 2024).
breast carcinoma (6 papers, 2017 to 2025). "High-expressed PSMA family genes (e.g., PSMA2, PSMA3, PSMA4, PSMA6, and PSMA7) in breast cancer tissues are reported to be linked to a poor OS of the cancer, but higher levels of PSMA5 and PSMA8 are indicative of better clinical outcomes." (PMID 41141246, 2025). "In the present study, we found that high expression of PSMA1-4 and PSMA6-7 was significantly associated with worse prognosis in breast cancer, while PSMA5 was related to better OS, RFS and DMFS." (PMID 27966459, 2017). "A previous analysis of PSMAs in breast cancer has indicated that, except for PSMA5, the expression of standard proteasome α‐subunits was associated with worse survival." (PMID 40862469, 2025). "PSMA5 was shown to be upregulated in nine types of cancers by 25 studies and downregulated in breast cancer and myeloma by two analyses." (PMID 27966459, 2017).
myeloma (4 papers, 2013 to 2022). "We found that the proteasome subunit gene PSMA5 is upregulated in myeloma SP cells." (PMID 23469177, 2013). "Moreover, CCNB1, AURKB, EZH2 and PSMA5 were also upregulated in the SPs from eight primary myeloma samples." (PMID 23469177, 2013). "However, other studies showed that the suppression of PSMA5 could strengthen the sensitivity of myeloma to bortezomib." (PMID 35421138, 2022). "PSMA5 was significantly upregulated in endometrial cancer, while PSMA6 was significantly upregulated in multiple myeloma patients and pancreatic ductal carcinoma cell models." (PMID 34943457, 2021).
COVID-19 (3 papers, 2022 to 2024). A disease caused by infection with severe acute respiratory syndrome coronavirus 2. "We observed PSMA4 and PSMA5 overexpression in COVID-19 patients." (PMID 35327634, 2022). "Multiple proteasome subunits (e.g., PSMA1, PSMA5, PSMA6, PSMA7, and PSMB1) were upregulated in COVID-19 patients, especially during the acute phase of disease, potentially contributing to the dysregulation of proteasome activity." (PMID 38965561, 2024). "Fifteen proteasomal proteins showed an increase in serum levels of COVID-19 patients, most notably PSMA7, PSME1, PSMB3, PSMA4 and PSMA5, whereas PSMD2 was the only one with decreased levels." (PMID 37739942, 2023). "Regarding the expression of 20S subunits in the α- and β-ring the mRNA expression of PSMA4, PSMA5, PSMB2, PSMB9, PSMB10 significantly increased in COVID-19 patients (COV) when compared to healthy control (HC)." (PMID 35327634, 2022).
glioma (3 papers, 2021 to 2024). A benign or malignant brain and spinal cord tumor that arises from glial cells (astrocytes, oligodendrocytes, ependymal cells). "In addition, it was suggested that c-FLIP and Mcl-1 were downregulated when treated with carboplatin in glioma cells was because of the increased activity of proteasome subunit alpha 5 (PSMA5)." (PMID 34065991, 2021). "Thus, the molecular mechanism of carboplatin resistance occurs through the regulation of Mcl-1 and c-FLIP by the elevation of Nrf2-dependent PSMA5 expression in glioma cells." (PMID 34065991, 2021). "In the present study, PSMA5 and PSMB6 were found to be highly expressed in gliomas, while PSMB10 was found to be lowly expressed by integrating the TCGA and GTEx databases’ glioma sample analyses." (PMID 34868920, 2021). "The results showed that PSMB6, PSMA5, UBB, and PSMD12 were significantly downregulated, and PSMB10 was significantly upregulated in gliomas." (PMID 34868920, 2021). "This study found the prognostic predictive values of the hypoxia-related genes PSMB10, PSMD12, UBB, PSMA5, and PSMB6 for glioma and provided ideas and entry points for the progress of hypoxia-related glioma." (PMID 34868920, 2021). "The results showed that PSMB6, PSMA5, UBB, and PSMD12 were highly expressed in the glioma tissues, while PSMB10 was lowly expressed in the glioma tissues compared with the normal tissues." (PMID 34868920, 2021). "In this study, our objective was to analyse whether SMB6, PSMD9, UBB, PSMD12, PSMB10, PSMA5, and PSMD14 are independent prognostic factors for glioma." (PMID 34868920, 2021). "PSMB10, PSMD12, UBB, PSMA5, and PSMB6 were found to be independent predictors of glioma prognosis." (PMID 34868920, 2021). "Univariate and multifactorial COX regression analyses were used to determine that PSMB10, PSMD12, UBB, PSMA5, and PSMB6 may be independent prognostic factors for gliomas." (PMID 34868920, 2021). "Notably, PSMB10, PSMD12, UBB, PSMA5, and PSMB6 were found to be independent prognostic predictive markers for glioma." (PMID 34868920, 2021). "In addition, PSMB6, PSMA5, UBB, and PSMD12 were lowly expressed, while PSMB10 was highly expressed, in the TCGA and GTEx integrated glioma samples and normal samples, which were verified through protein expression levels in the Human Protein Atlas database." (PMID 34868920, 2021).
melanoma (3 papers, 2016 to 2020). A malignant, usually aggressive tumor composed of atypical, neoplastic melanocytes. "With respect to melanoma, the mRNA expression levels of PSMA1, PSMA3, PSMA5 and PSMA6 were upregulated in melanoma compared with normal tissues according to Haqq's dataset." (PMID 27966459, 2017).
bladder cancer (2 papers, 2017 to 2020). "For bladder cancer, Oncomine included only four datasets that were available for cancer vs. normal analysis, of which Dyrskjot and Sanchez-Carbayo's dataset respectively showed elevated expression levels of PSMA2 and PSMA5 in bladder cancer compared to normal tissues." (PMID 27966459, 2017).
lung carcinoma (2 papers, 2017 to 2021). "On the other hand, a survey of the human Cancer Cell Line Encyclopedia (CCLE) identified H1975 and H3255 cells (two lung cancer lines) with reduced copy numbers of the PSMA5 gene (encoding α5)." (PMID 34831298, 2021). "PSMA5 was also shown to be overexpressed in lung cancer according to Garber's datasets." (PMID 27966459, 2017). "In lung cancer, PSMA1-2, PSMA4 and PSMA5 were correlated with better prognosis, whereas PSMA6 and PSMA7 predicted worse survival outcomes." (PMID 27966459, 2017).
ovarian carcinoma (2 papers, 2020 to 2024). A malignant neoplasm originating from the surface ovarian epithelium. "Kaplan–Meier curve analysis revealed a significant correlation (p < 0.05) between low expression of HSP90AA1, HSPA8, PSMA5, and SOD1 and prolonged overall survival (OS) in ovarian cancer patients." (PMID 38166541, 2024).
Sepsis (2 papers, 2021 to 2022). Sepsis is defined as life-threatening organ dysfunction caused by a dysregulated host response to infection. "Previous studies have reported that PSMA5 mRNA expression levels are highly expressed in the serum of patients with sepsis presenting with hypoxemia but are lowly expressed in an in vitro hypoxia model." (PMID 34868920, 2021).
autoimmune disease (1 paper, 2021). A disorder resulting from loss of function or tissue destruction of an organ or multiple organs, arising from humoral or cellular immune responses of the individual to their own tissue constituents. "The non-CHD indications of clinically used drugs included dyslipidemias (PPARA), type 2 diabetes (PPARG and NDUFA13), autoimmune diseases (TNF), neoplasms (RAF1 and PSMA5), circulatory disorders (ABCA1, PLG, ITGB3, and F2), and alcohol-dependency (ALDH2)." (PMID 34675202, 2021).
colorectal cancer (1 paper, 2017). A primary or metastatic malignant neoplasm that affects the colon or rectum. "Combined with higher proteasome activity, increased levels of PSMA5 and PSMAD4 could be detected in colorectal cancer." (PMID 27966459, 2017).
esophageal cancer (1 paper, 2021). A primary or metastatic malignant neoplasm involving the esophagus. "Interestingly, other proteasome subunits were also expressed highly in EC and the elevated expression of PSMA2, PSMA5, PSMC6, PSMD5, PSMD10 indicated poor prognosis of EC patients respectively, which revealed a crucial role of 26S proteasome in esophageal cancer." (PMID 33897885, 2021).
head and neck squamous cell carcinoma (1 paper, 2017). A squamous cell carcinoma that arises from any of the following anatomic sites: lip and oral cavity, nasal cavity, paranasal sinuses, pharynx, larynx, and salivary glands. "In addition, Ginos's dataset showed an increased expression level of PSMA5 in head and neck squamous cell carcinoma." (PMID 27966459, 2017).
hepatocellular carcinoma (1 paper, 2024). A malignant tumor that arises from hepatocytes. "PSMA5 knockdown inhibited migration and invasion of hepatocellular carcinoma (HCC) cells." (PMID 38415977, 2024).
kidney cancer (1 paper, 2017). Primary or metastatic malignant neoplasm involving the kidney. "Moreover, only PSMA6 and PSMA5 were not overexpressed in colorectal and kidney cancer, respectively." (PMID 27966459, 2017).
kidney chromophobe cell carcinoma (1 paper, 2017). "Compared with normal kidney tissue, PSMA1, PSMA3 and PSMA7 were upregulated in kidney chromophobe cell carcinoma, whereas PSMA5 was downregulated." (PMID 27966459, 2017).
lymph node metastasis (1 paper, 2024). "In addition, the upregulation of PSMA5 expression is positively correlated with lymph node metastasis and poor prognosis in patients with LUAD." (PMID 38782996, 2024).
lymphopenia (1 paper, 2022). Reduction in the number of lymphocytes. "Patients with high PSMA4 and PSMA5 mRNA expression suggested more acute lymphopenia, more severe hypoxemia and higher concentrations of C-reactive protein and ferritin in plasma." (PMID 35327634, 2022).
ovarian tumor (1 paper, 2024). "Additionally, the expression levels of HSPA8 and SOD1 were higher in high-grade serous ovarian cancer samples compared to non-malignant ovarian tumor tissues, while RPL13A, PSMA5, and RPSA showed the opposite trend." (PMID 38166541, 2024).
tumor (13 papers, 2015 to 2025). "Among these 211At-labeled PSMA ligands, [211At]At-PSMA5 showed the most favorable biodistribution and planar images of [211At]At-PSMA5 revealed the tumor tissue at 3 and 24 h postinjection." (PMID 38564087, 2024). "[211At]PSMA1 also showed a good treatment effect, but it showed relatively larger tumor size than [211At]PSMA5 did." (PMID 36344651, 2023). "[211At]PSMA1 also showed a substantial treatment effect; however, the tumor size was relatively larger compared to that with [211At]PSMA5." (PMID 36344651, 2023). "The result showed that [211At]PSMA5 exhibited the best tumor retention and excellent tumor growth suppression in LNCaP xenograft models compared to [211At]PSMA1." (PMID 36344651, 2023). "Regarding the treatment effect, excellent tumor growth suppression was observed in LNCaP xenograft after the administration of [211At]PSMA5." (PMID 36344651, 2023). "Previous studies demonstrated that the upregulation of PSMA5, by activating the key Nrf2/ARE signalling pathway, played a critical role in the mechanism of inducing tumour cell apoptosis caused by combined chemotherapy regimens." (PMID 35421138, 2022). "In therapeutic experiments, [211At]At-PSMA5 showed excellent tumor growth suppression in LNCaP tumor-bearing mice without significant body weight loss." (PMID 38564087, 2024). "Therefore, [211At]PSMA5 showed better tumor-to-kidney uptake than [211At]PSMA6 did." (PMID 36344651, 2023). "Knockdown of exosomal proteasome subunit alpha 5 (PSMA5) derived from HCC cells impeded M2 macrophage polarization via abrogating JAK2/STAT3 signaling pathway, leading to inhibited tumor cell proliferation, invasion, and migration." (PMID 40264760, 2025). "In the cellular uptake analysis, [211At]PSMA5 showed higher uptake than [211At]PSMA1, corresponding to the in vivo uptake in tumor xenograft models." (PMID 36344651, 2023). "When grouped by tumor stage, all seven PSMAs showed different prognostic values in stage 1, whereas only PSMA1, PSMA2 and PSMA5 were correlated with OS or PPS in stage 2." (PMID 27966459, 2017). "Notably, some previously reported genes, such as PSMA5 and KIF11, can be treated as potential therapeutic targets for tumours." (PMID 35421138, 2022). "As no significant change in tumor growth was observed in the non-radiolabeled PSMA compounds, the antitumor effect of [211At]PSMA5 was attributed to the α-particle emission from 211At." (PMID 36344651, 2023).
cancer (8 papers, 2017 to 2025). A tumor composed of atypical neoplastic, often pleomorphic cells that invade other tissues. "HCC cell‐secreted exosomal PSMA5 knockdown hinders M2 polarization to suppress cancer progression by restraining JAK2/STAT3 signaling." (PMID 38415977, 2024). "In particular, H2AFV, CEBPB, SEC61G, GLRX, and PSMA5 exhibited dramatically worse overall survival in multiple cancers, which was consistent with their high expression in a variety of cancer tissues." (PMID 37251379, 2023). "In a group of datasets including Perou, Curtis, Sorlie, Sorlie 2, Radvanyi, and Zhao, the mRNA level of PSMA5 was significantly overexpressed in cancer tissues." (PMID 27966459, 2017). "Subsequently, whether the role of PSMA5 in suppressing HCC cancer progression is attributed to HCC cell‐secreted exosome‐mediated intercellular transport of PSMA5 into macrophages was investigated." (PMID 38415977, 2024). "However, in humans, it has been hypothesized that renal function tends to decline due to past cancer treatments, and the initial clinical dose of [211At]PSMA5 should be determined carefully." (PMID 36344651, 2023). "siRNA-mediated KD of PSMA5 reversed the downregulation of Bcl-xL, and inhibited Pep A plus TRAIL-induced apoptosis in multiple cancer cell lines." (PMID 35121737, 2022).
infection (5 papers, 2017 to 2024). The state of being infected such as from the introduction of a foreign agent such as serum, vaccine, antigenic substance or organism. "The global network notably recognizes six proteins (EPHA2, FBL, PFKM, PSMA5, SSR1, and TFRC) for their involvement in the infection of cells (p: 9.58 × 10− 4)." (PMID 31159726, 2019). "The extracellular presence of a proteasome subunit PSMA5 is intriguing since extracellular proteasomes have been previously identified, and their subunits possibly present in extracellular vesicles according to the Exocarta database, but they have not been studied in the context of infection." (PMID 29158431, 2018). "Extracellular levels of PSMA5 upon infection were not significantly affected by GW4869 treatment, suggesting that PSMA5 might not be a target of secretion via exosomes." (PMID 29158431, 2018).
cardiovascular diseases (1 paper, 2023). "Similarly, we found an interaction between the SNP rs599839, associated with cardiovascular diseases, and the gene PSMA5, that was present among immune cell types (black-white heatmap)." (PMID 37428809, 2023).
infectious disease (1 paper, 2024). A disorder directly resulting from the presence and activity of a microbial, viral, or parasitic agent in humans. "Overrepresentation analyses of upregulated proteins yielded six Reactome pathways enriched, highlighting “HSA-5663205: Infectious disease” (strength = 1.19; FDR = 0.003), which included the proteins RPL18A, PSMA5, HSPA1B, RPL35A, and ISG15." (PMID 39409176, 2024).
PSMA5 also shares sentences with these, for which no sentence is quoted: lung adenocarcinoma (3 papers); colon cancer (2); liver cancer (2); Alport syndrome (1); Alzheimer disease (1); Cachexia (1); cervical cancer (1); dyslipidemias (1); endometrial cancer (1); epilepsy (1); head and neck cancer (1); infertile (1); kidney renal cancer (1); memory impairment (1); multiple myeloma (1); non-small cell lung carcinoma (1); pancreatic cancer (1); pancreatic ductal carcinoma (1); psoriasis (1); serous ovarian cancer (1); transitional cell papilloma (1); type 2 diabetes (1); varicocele (1).